CXCL9 (C-X-C motif chemokine ligand 9)
Diseases named in the same sentence as CXCL9 in open-access papers (continued):
Sharing a sentence is not in itself a finding about the gene and the disease.
head and neck squamous cell carcinoma (10 papers, 2020 to 2025). A squamous cell carcinoma that arises from any of the following anatomic sites: lip and oral cavity, nasal cavity, paranasal sinuses, pharynx, larynx, and salivary glands. "Recent studies have demonstrated that the expression of CXCL9 and SPP1 (CS) exhibits a strong prognostic association, surpassing traditional M1 and M2 markers, as revealed by single-cell analysis in head and neck squamous cell carcinoma." (PMID 40936719, 2025). "In head and neck squamous cell carcinoma, CXCL9 enhances immune responses and infiltration, predicting the efficacy of immunotherapy." (PMID 38919494, 2024). "It has been illustrated that the expression of CXCL9 and SPP1 in macrophages at the single-cell level in head and neck squamous cell carcinoma is largely mutually exclusive, with CS polarity serving as a predictive factor." (PMID 40936719, 2025). "Moreover, the exclusive expression of CXCL9 and SPP1 in TAMs within ccRCC samples corroborates with the findings in head and neck squamous cell carcinoma." (PMID 38222314, 2024). "Another example of a recently identified biomarker exclusively expressed on distinct subpopulations of TAMs is CXCL9 and SSP1 in head and neck squamous cell carcinoma (HNSCC)." (PMID 39516356, 2024). "Similarly, in head and neck squamous cell carcinoma, the knockout of K17 in immunocompetent mouse model also resulted in tumor regression due to alterations in IFN ‐γ and CXCL9, and PD-L1 expression and increased CD8+ T-cell infiltration, thereby sensitizing tumors to immune-checkpoint blockade." (PMID 38730319, 2024).
lupus (10 papers, 2010 to 2025). "For example, although they bind the same CXCR3 receptor, CXCL9 is predominant in lupus-prone mice but CXCL10 is predominant in SLE patients." (PMID 37567910, 2023). "We showed that globally reducing FLI-1 levels in a lupus prone mouse strain reduced renal Cxcl9 and Cxcl10 gene expression and renal-infiltrating CXCR3+ T cells, and that FLI-1 can upregulate Cxcr3 promoter activity in T cells." (PMID 37790939, 2023). "Two different combined inflammatory and lymphoid chemokine scores were investigated using CCL2, CXCL10 and CCL19 (score used successfully in lupus) and CXCL9, CXCL10, CXCL13 and CCL19 data." (PMID 24278364, 2013). "Previous studies have shown that Fli-1 is a positive regulator of CCL2, CCL3, CCL4, CCL5, CXCL9, and CXCL10 in the kidneys of Fli-1 heterozygote knockout mice with lupus and CXCL5 in dermal small vessels from Fli-1 knockout mice." (PMID 40305194, 2025). "In this regard, it has been reported that levels of CXCL9, CXCL10 and CXCL11 correlate with lupus disease activity." (PMID 21050432, 2010). "Thus, renal CXCL9 and CXCL10 are decreased at the transcript and protein levels in lupus prone MRL/lpr Fli-1+/−- mice and suggests FLI-1 modulates CXCL10, CXCL9 expression in the kidneys during lupus nephritis." (PMID 37790939, 2023). "Systemic lupus erythematosus mice had a 3 to 5-fold higher renal cortical mRNA expression of lymphocyte-specific CXC chemokines (CXCL9,10,13, and 16) and CXC receptors (CXCR3 and 4) that contribute to SLE pathophysiology." (PMID 31133860, 2019). "Although IFN-γ can also induce CD64 expression, its contribution to the interferon signature in SLE may be limited, as genes specifically induced by IFN-γ (that is, CXCL9) are not known to be upregulated in lupus patients." (PMID 20478071, 2010).
pneumonia (10 papers, 2011 to 2025). An acute, acute and chronic, or chronic inflammation focally or diffusely affecting the lung parenchyma, caused by an infection in one or both of the lungs (by bacteria, viruses, fungi, or mycoplasma.). "The upregulation of CXCL9 was unique to the pneumonia cases, indicating that CXCL9 is involved in the pathogenesis of psittacosis." (PMID 36119044, 2022). "Upregulation of the IFN-γ responsive genes Nos2 and Cxcl9 during pneumonia were confirmed by RT-qPCR in independent samples." (PMID 28900269, 2017). "The adaptive-immunity (Th1/Th17)-related CXCL10/IP-10, CXCL9/MIG and IL-17A however, were markedly suppressed in severe pH1N1 pneumonia (2–27 times lower than seasonal influenza; P−values<0.01)." (PMID 22022504, 2011). "There was sustained activation of the proinflammatory cytokines (IL-6, CXCL8/IL-8, CCL2/MCP-1, sTNFR-1) in severe pH1N1 pneumonia; the CXCL10/IP-10, CXCL9/MIG and IL-17A responses remained largely suppressed during the hospital course." (PMID 22022504, 2011). "The greater expression of interferon-induced genes in S. pneumoniae infection was also reflected at the protein level as shown by the significantly higher amounts of interferon-induced CXCL9 and CXCL10 in serum of S. pneumonia-infected mice in comparison with S. aureus-infected or PBS-treated mice." (PMID 29988532, 2018).
prostate carcinoma (10 papers, 2019 to 2024). A carcinoma that arises from epithelial cells of the prostate gland. "Taking prostate cancer as an example, CXCL9 promotes tumor progression by inhibiting cytokines produced by T cells, which is evident in the severity of pathology, increased cellular proliferation, and reduced patient survival rates." (PMID 38791448, 2024). "Consistent with this, some/many CD8 T cells were located adjacent to MNPs and spatial transcriptomic analysis of prostate cancer confirmed colocalization of the MAC-MT signature with CXCL9/10 and with CD8 T cells." (PMID 34936871, 2021). "Additionally, studies have found a positive correlation between the expression of CXCL9 and the clinical pathological stages of prostate cancer." (PMID 38791448, 2024). "CXCL9 promotes the progression of prostate cancer by inhibiting the cytokines from T cells." (PMID 35675043, 2022). "We further confirmed that Cxcl5 was downregulated, and Cxcl9/10 were upregulated in the FACS-isolated stromal cells from both RM-1 xenografts and prostate cancer tissues of Col1a2-Foxf2-TRAMP mice as compared to their respective controls." (PMID 36369237, 2022). "Furthermore, chemokine CXCL9 secreted by the prostate cancer cells was shown to mediate CD4+ T cell recruitment to the prostate cancer regions, and CXCL9 blockage suppressed CD4+T cell migration towards the prostate cancer cells." (PMID 36836690, 2023).
type 1 diabetes (10 papers, 2012 to 2025). "Evidence from both type 1 diabetes animal models and human pancreatic organ donors with recent-onset type 1 diabetes identified CXCL9 and CXCL10 as key chemokines that induce the attraction of autoreactive T cells bearing the corresponding chemokine receptor CXCR3 to pancreatic islets." (PMID 37458220, 2023). "Importantly, T cells and CXCL9-positive macrophages were also observed in the islets of a cancer patient who received ICIs and developed type 1 diabetes." (PMID 35511238, 2022). "The simultaneous upregulation of chemokines that promote (CXCL10, CXCL9) and protect against (CCL17, CCL22) type 1 diabetes suggests a complex immune response to PET microplastics." (PMID 40597598, 2025). "Moreover, CXCL9, in conjunction with CXCL10, also changes the mass and function of β-cells, and deletion of CXCR3 in mice delays the onset of type 1 diabetes." (PMID 40597598, 2025).
autoimmune thyroiditis (9 papers, 2021 to 2025). "Additional chemokines, such as CXCL10, CXCL9, CCL2, and CCL22, are expressed in both psoriatic and thyroid autoimmune diseases." (PMID 40863211, 2025). "These chemokines play an important role in the pathogenesis of thyroid autoimmune diseases, and studies have shown that IFN-γ induces the secretion and expression of CXCL10, CXCL9 and CXCL11 in a dose-dependent manner." (PMID 38567309, 2024).
Autoimmunity (9 papers, 2004 to 2026). The occurrence of an immune reaction against the organism's own cells or tissues. "Immunomodulation and autoimmunity: RE was associated with the downregulation of proinflammatory chemokines CXCL9 and CCL20, both linked to HT risk in our previous study." (PMID 41301428, 2025). "We then assessed the associations of CXCL9, CXCL10, and CXCL11, that were different between groups, with clinical characteristics, diagnosis, and treatment responsiveness to identify biomarkers of inflammation in ILD with background autoimmunity." (PMID 33137121, 2020). "Our AUCs for serum CXCL9, CXCL10 and CXCL11 in the differential diagnosis of CVD–ILD from IPAF and IPF suggest that these serum chemokines may be diagnostic biomarkers of ILD with autoimmunity." (PMID 33137121, 2020). "This study demonstrated that in patients with CVD–ILD and IPAF with background autoimmunity, serum and BALF levels of CXCL9, CXCL10, and CXCL11 were significantly higher than those in patients with IPF." (PMID 33137121, 2020). "The TSH-lowering effect of selenium supplementation is unlikely to be related to changes in humoral markers of autoimmunity and/or circulating CXCL9." (PMID 36266640, 2022). "Serum CXCL9, CXCL10, and CXCL11 are potential biomarkers for autoimmune inflammation and predictors of the immunosuppressive therapy responses in ILD with background autoimmunity." (PMID 33137121, 2020). "CXCR3 binds and traffics toward its IFNγ-inducible ligands, CXCL9, 10, and 11, which are expressed primarily in activated CD8+ T cells, NK cells, and CD4+ TH1 cells and play critical roles in recruiting and retaining T cells during infection, autoimmunity and cancer." (PMID 39409972, 2024). "Serum CXCL9, CXCL10, and CXCL11 may reflect autoimmune inflammation of ILD and work as biomarkers to predict the response to immunosuppressive therapy in the management of ILD with background autoimmunity." (PMID 33137121, 2020). "Our results suggest that high serum CXCL9, CXCL10, and CXCL11 levels may reflect reversible inflammation and that these chemokines are predictive biomarkers of the response to immunosuppressive therapy in ILD with background autoimmunity." (PMID 33137121, 2020).
bladder cancer (9 papers, 2015 to 2025). "In bladder cancer, the tumor-associated dendritic cells were found to secrete CXCL9, increasing PD-L1 expression in the tumor cells via the CXCR3/STAT3/AKT signaling pathway, thus resulting in the inhibition of anti-tumor adaptive immunity." (PMID 36131933, 2022). "In bladder cancer, CXCL9 expression is negatively correlated with the recurrence rate, and high CXCL9 expression can improve the prognosis of bladder cancer patients." (PMID 35292033, 2022). "Such novel findings indicated that bladder cancer cells enhanced CXCL9 in TADCs, which significantly up-regulated PD-L1 expression in cancer cells by activating the CXCR3-related STAT3/Akt signaling." (PMID 33407095, 2021). "To further understand how the increased CXCL9 expression by TADCs regulated PD-L1 expression in bladder cancer T24 cells, we tested the effect of CXCL9 treatment on the expression of STAT3 and Akt activation in T24 cells by Western blot." (PMID 33407095, 2021). "In this study, we found that CXCL9 secreted by TADCs enhanced PD-L1 expression in bladder cancer T24 cells, which was abrogated by the CXCR3 antagonist AMG487." (PMID 33407095, 2021). "TADCs produced high levels of CXCL9 that increased PD-L1 expression in bladder cancer T24 cells by activating the CXCR3-related signaling." (PMID 33407095, 2021). "Given that anti-PD-1 and anti-PD-L1 are promising to treat some types of solid cancers the CXCL9/CXCR3/PD-L1 axis may be new therapeutic targets for intervention of bladder cancers." (PMID 33407095, 2021). "Hence, bladder cancer T24 cells enhanced the production of CXCL9 by the LPS-treated DCs." (PMID 33407095, 2021). "Therefore, our findings suggest that the CXCL9/CXCR3/PD-L1 axis may be the potential therapeutic targets for bladder cancer." (PMID 33407095, 2021). "Intriguingly, blockade of PGE2 synthesis has been shown to increase the expression of CXCL9 and CXCL10 in murine models of cutaneous melanoma, as well as our murine bladder cancer models (unpublished observations)." (PMID 35347124, 2022). "Expression of the CXC subfamily chemokines (CXCL9, CXCL10, and CXCL13) and of the CC subfamily chemokine CCL18 was consistently found to be higher in bladder cancer patients in the CLR-high group than in the patients in CLR-low group." (PMID 36131933, 2022). "Bladder cancer tissues spontaneously expressed high levels of the granulocyte/MDSC-attractant CXCL8 and Treg-attractant CCL22, but only marginal levels of the CTL-attracting chemokines: CCL5, CXCL9 and CXCL10." (PMID 25806105, 2015). "Hence, STAT3 activation is crucial for inducing PD-L1 expression in tumor cells and inhibition of STAT3 activity may inhibit the CXCL9/CXCR3 signaling-induced PD-L1 expression, benefiting bladder cancer patients." (PMID 33407095, 2021). "By means of a 34‐cytokine and chemokine immunoassay panel, we revealed that chemokines including CCL3, CCL4, CCL5, CXCL9, and CXCL10, are robust negative correlated with expression of BCAT2 in human and murine bladder cancer cell." (PMID 36642843, 2023).
cervical cancer (9 papers, 2016 to 2025). A primary or metastatic malignant neoplasm involving the cervix. "Analysis of TCGA datasets indicated that elevated IFN‐Mac_CXCL9 signature expression is associated with improved survival in patients with ovarian, endometrial and cervical cancers." (PMID 41275425, 2025). "The expression ratio of CXCL9 to SPP1 was analyzed in cervical cancer patients using data from the Gene Expression Omnibus (GEO) database, which revealed significant differences." (PMID 40936719, 2025). "Current research on cervical cancer has revealed distinct functional roles of CXCL9 and secreted SPP1 in tumor pathogenesis." (PMID 40936719, 2025). "We further performed IHC on CXCL9/10/11/13 to detect their protein expression in cervical cancer tissues and adjacent tissues." (PMID 34321012, 2021). "These were consistent with the findings in the databases and also further verified the transcriptional expression of CXCL9/10/11/13 in cervical cancer." (PMID 34321012, 2021). "The mRNA expression of CXCL9/10/11/12/13 in cervical cancer tissues and adjacent cancer tissues was also examined by qRT-PCR." (PMID 34321012, 2021). "Notably, we uncovered a compelling association between CCL5, CXCL9, and CXCL10 and key prognostic factors, encompassing overall survival and progression-free survival, in cervical cancer, as observed within TCGA dataset." (PMID 38550593, 2024). "However, cervical cancer studies had demonstrated that the IHC of CXCL9 was elevated in tumor tissues compared to normal tissues but did not correlate with the outcome." (PMID 38957805, 2024). "However, CXCL9/10/11, as anti-angiogenic chemokines, inhibited the angiogenesis of cervical cancer through its receptor CXCR3-B." (PMID 34321012, 2021). "This suggested that CXCL9 was involved in the development of cervical cancer." (PMID 27726306, 2016). "However, the expression patterns, prognostic significance, and underlying molecular mechanisms of CXCL9 and SPP1 in cervical cancer remain unclear." (PMID 40936719, 2025). "We compared the expression differences of CXCL9 and SPP1 between normal cervical tissues and cervical cancer samples." (PMID 40936719, 2025). "CXCL9 and SPP1 exhibit prognostic significance in cervical cancer patients." (PMID 40936719, 2025). "Therefore, this study aims to explore the expression profiles of CXCL9 and SPP1 in cervical cancer tissues and assess their potential clinical value." (PMID 40936719, 2025). "With this in mind, our subsequent investigation delves into the intricate correlation between the expression levels of STING downstream genes, CCL5, CXCL9, and CXCL10, and their influence on the overall immune infiltration status within the cervical cancer TME." (PMID 38550593, 2024). "The results suggested that CXCL9/10/11 in the tumor microenvironment may recruit CD8+ T cells and NK cells through the CXCL9–11/CXCR3 axis, thereby improving the survival of cervical cancer patients by inhibiting the development and progression of tumors." (PMID 34321012, 2021).
dermatitis (9 papers, 2016 to 2025). An inflammatory process affecting the skin. "In this process, chemokines induced by interferon‐g (such as CXCL9, CXCL10, and CXC11) play a significant role in attracting inflammatory cells to infiltrate the interface dermatitis." (PMID 38799517, 2024). "In this study, immunofluorescence and qPCR analysis showed that MLT significantly reduced the infiltration of CD4+ T cells in rosacea-like dermatitis and suppressed the expression of Th1-related genes (IFN-γ, CCR5, CXCL9, CXCL10) and Th17-related genes (STAT3 and IL-20) in rosacea-like dermatitis." (PMID 34899707, 2021). "However, a similar dichotomy in the expression of CXCL9 and CXCL10 (and CXCL11) has been described before for different human skin disorders." (PMID 31447864, 2019). "In addition, CXCL9 expression is strongly upregulated in PGRN KO mice and its level is correlated with severity of inflammation in a dermatitis model." (PMID 26892362, 2016). "Chemokine genes, including CXCL9 and CXCL10, which are regulated by T-cell effector cytokines, exhibit different levels of upregulation in hapten-specific skin inflammation but are not induced during irritant-induced skin inflammation." (PMID 37513911, 2023).
macrophage activation syndrome (9 papers, 2019 to 2024). A complication of rheumatic disease that is caused by excessive activation and uncontrolled proliferation of T lymphocytes and well-differentiated macrophages. "In our case, we observed positive results for chemokine ligand 9 (CXCL9) and soluble IL-2 receptor, which are among the features included in the Delphi International Survey for diagnosing macrophage activation syndrome (MAS)." (PMID 38910713, 2024). "Increased levels of IFNγ-induced chemokines such as CXCL9, CXCL10, and CXCL11 were found to be associated with sJIA complicating macrophage activation syndrome." (PMID 35268506, 2022). "In the current study, we sought to determine the role of CXCL9 in pathogenesis in murine models of both Familial HLH (prf1−/−) and Toll Like Receptor (TLR) 9 repeated stimulation induced Macrophage Activation Syndrome (MAS), a form of secondary HLH." (PMID 37516815, 2023).